FHIT (fragile histidine triad diadenosine triphosphatase)
Diseases named in the same sentence as FHIT in open-access papers (continued):
Sharing a sentence is not in itself a finding about the gene and the disease.
adenoma (6 papers, 2001 to 2022). A neoplasm arising from the epithelium. "In particular, we identified three genes (MLH1, ATM and FHIT) differentially methylated in adenomas that recurred during the five-year follow up." (PMID 25091577, 2014). "In particular, MLH1, ATM and FHIT gene promoters were found to be significantly hypermethylated in recurring adenomas." (PMID 25091577, 2014). "Expression of FHIT is the highest in adrenocortical hyperplasia, lowest in carcinoma, and middle in adenoma." (PMID 18366613, 2008). "It suggests that the degree of FHIT gene abnormal transcription and FHIT protein deletion or reduction in adrenocortical carcinoma is more serious than that in adenoma and hyperplasia." (PMID 18366613, 2008). "To define the role of the FHIT gene in the development of ovarian cancer, we have examined 33 ovarian carcinomas, 2 borderline tumours and 10 benign adenomas for the presence of FHIT gene alterations." (PMID 11461085, 2001). "Loss of normal FHIT transcript was observed in 5/33 carcinomas (15%) but not in 2 borderline tumours or 10 benign adenomas." (PMID 11461085, 2001). "The promoters of three genes (FHIT, MLH1 and ATM) were found to be hypermethylated in a significantly higher fraction of adenomas that recurred compared to non recurring lesions." (PMID 25091577, 2014). "The results of this study show that combined detection of the expression of FHIT, Ki-67 and PCNA in hypercortisolism of adrenocortical carcinoma, adenoma and hyperplasia is valuable." (PMID 18366613, 2008). "We then compared the mean methylation levels of gene promoters in R and NR patients, confirming that MLH1, ATM and FHIT were significantly differentially methylated in adenomas on the basis of the presence or not of lesion recurrence." (PMID 25091577, 2014). "The expression levels of FHIT, Ki-67 and PCNA in hypercortisolism of various adrenocortical diseases are useful for distinguishing adrenocortical carcinoma, adenoma and hyperplasia but none of them are high characteristic." (PMID 18366613, 2008).
bladder cancer (6 papers, 2006 to 2025). "FHIT protein deficiency has been also reported in bladder cancer, mainly in high-grade tumors." (PMID 33920347, 2021). "Reduced concentration of histidine in bladder cancer patients may correlate with a lower activity of FHIT protein." (PMID 33920347, 2021). "BBN(N-butyl-N-(-4-hydroxybutyl)- nitrosamine)-induced urinary bladder cancer could be prevented in FHIT knock-out mouse by Rofecoxib, a cox-2 inhibitor." (PMID 29296239, 2017). "At present, FHIT and WWOX promoter methylation associated with the loss of gene expression has been reported for various types of cancers, including lung, breast, esophageal and bladder cancer." (PMID 24137446, 2013).
oral cancer (6 papers, 2003 to 2021). "Further support for the role of FHIT in the DDR comes from DNA methylome analysis showing that epigenetic silencing of FHIT as a determining factor for radiosensitivity in oral cancer." (PMID 27977694, 2016). "Nevertheless, the present study is the first to demonstrate that epigenetic silencing of FHIT can initiate radioresistance in irradiated human oral cancers cells." (PMID 25460508, 2015). "Clinically, promoter hypermethylation of FHIT inversely correlated with its expression and independently predicted both locoregional control and overall survival in 40 match-paired oral cancer patient samples." (PMID 25460508, 2015). "Restoring FHIT expression has been observed to restore pChk2 activity and then re-radiosensitization of oral cancer cells." (PMID 25460508, 2015). "Epigenetically or ectopically restoring FHIT suppresses tumor growth and enhances radiosensitivity in oral cancer cells." (PMID 25460508, 2015). "To further examine a clinical role for FHIT in oral cancer progression, we investigated its promoter methylation and expression in 40 match-paired, paraffin-embedded oral cancer patient samples." (PMID 25460508, 2015). "In conclusion, we have identified FHIT as epigenetically silenced by DNA methylation and histone modification in radioresistant oral cancer cells." (PMID 25460508, 2015). "Taken together, these results strongly suggest that epigenetic modifications contribute to the process of radioresistance via down-regulation of FHIT in oral cancer cells." (PMID 25460508, 2015). "In this study, high promoter methylation of FHIT (>10%) can be observed in 55% (22/40) of oral cancer patient samples." (PMID 25460508, 2015). "In an early study using RNA extracted from oral carcinomas in South Africa, FHIT transcription was examined by reverse transcription of RNA and PCR amplification of the cDNA product (RT–PCR) using primers within the FHIT open reading frame." (PMID 12771912, 2003). "Furthermore, hypermethylation of the FHIT promoter was inversely correlated with its expression, and served as an independent predictor of both overall survival and locoregional control in oral cancer patient samples." (PMID 29439529, 2018). "FHIT (Fragile histidine triad) gene, a triphosphate hydrolase involved in purine metabolism, is hypermethylated and consequently silenced in established radioresistant oral cancer cells." (PMID 29439529, 2018). "Other mechanisms such as genetic alteration may play a role in the down-regulation of FHIT in this group of oral cancer patients." (PMID 25460508, 2015). "Moreover, restoring expression of epigenetically repressed FHIT resensitized radioresistant oral cancer cells to ionizing radiation." (PMID 25460508, 2015). "Herein, we observed a role of FHIT in initiating radioresistance in irradiated oral cancer cells." (PMID 25460508, 2015). "To avoid the possibility of cell line effects, we investigated the radiosensitivity in another two oral cancer cell lines (SAS, SCC25), both of which endogenously underexpress FHIT." (PMID 25460508, 2015). "Using a methylation microarray, we identified promoter hypermethylation of FHIT (fragile histidine triad) in radioresistant OML1-R cells, established from hypo-fractionated irradiation of parental OML1 radiosensitive oral cancer cells." (PMID 25460508, 2015). "We then explored the correlation between FHIT expression and promoter methylation in a primary human oral keratinocyte (HOK) and four other oral cancer cell lines (OCSL, SCC25, SAS, and SCC4)." (PMID 25460508, 2015).
breast tumour (5 papers, 2003 to 2020). "Complete MHC-I cell surface downregulation or loss has been reported in around 50% of human breast tumors, and a further study aim was to explore the possible association between FHIT protein expression and MHC-I expression in human breast cancer cells." (PMID 32545680, 2020). "All breast tumors with decreased FHIT protein expression also showed loss of HLA-I surface expression; moreover, 33% of the breast tumors had no loss of HLA-I surface expression or FHIT protein expression." (PMID 32545680, 2020). "We showed a high significant association between FHIT protein expression loss and downregulation of HLA class I molecules on human breast tumors." (PMID 32545680, 2020). "The overall conclusion was that FHIT LOH results in growth advantage of breast tumour cells, is associated with an unstable genome and may be of prognostic value." (PMID 12771912, 2003). "Our results reveal for the first time that FHIT expression and MHC-I expression are significantly associated in human breast tumors (p < 0.001)." (PMID 32545680, 2020). "Finally, we also observed a direct correlation between FHIT expression and HLA-I surface expression in human breast tumors." (PMID 32545680, 2020). "We next examined whether this association between FHIT expression and MHC-I expression can be observed in human tumor cells, specifically choosing breast tumors because of their frequent complete loss of HLA-I cell surface expression (in ~50% of cases)." (PMID 32545680, 2020). "Loss of Fhit expression was significantly more frequent in the BRCA1 cancers compared with sporadic breast tumours (9% Fhit positive vs 68% Fhit positive), suggesting that the BRCA1 pathway is also important in protecting the FRA3B/FHIT locus from damage." (PMID 12771912, 2003). "FHIT gene markers were typed in 239 breast tumours and paired normal tissue, and results assessed relative to clinicopathologic factors and LOH at other regions." (PMID 12771912, 2003).
depression (5 papers, 2016 to 2025). "Eight SNPs corresponding to six protein-coding genes (TNXB, NCAM1, LTBP3, BTN3A2, DAG1, FHIT) were identified that were highly associated with depression." (PMID 39897774, 2025). "Genetic variants within the FHIT gene have been implicated in anxiety, comorbid depressive syndromes and alcohol dependence, mental stress and autism." (PMID 39897774, 2025). "They discovered one genome-wide significant locus mapping to the FHIT gene for this broad depression phenotype." (PMID 30626913, 2020). "We have identified six protein-coding genes associated with depression and primarily involved in inflammation (TNXB), neuroplasticity (NCAM1 and LTBP3), immune response (BTN3A2), cell survival (DAG1) and circadian clock modification (FHIT)." (PMID 39897774, 2025). "In addition, a recent GWAS meta-analysis has identified a new locus for depression within the FHIT gene." (PMID 39897774, 2025). "The present study identified six protein-coding genes associated with depression and primarily involved in inflammation (TNXB), neuroplasticity (NCAM1 and LTBP3), immune response (BTN3A2), cell survival (DAG1) and circadian clock modification (FHIT)." (PMID 39897774, 2025). "Our findings confirmed previous evidence for TNXB- and NCAM1 in the pathophysiology of depression and suggested new potential candidate genes (LTBP3, BTN3A2, DAG1 and FHIT) that warrant further investigation." (PMID 39897774, 2025). "Our findings confirmed previous evidence for TNXB- and NCAM1 in the pathophysiology of depression and suggested four new potential candidate genes (LTBP3, BTN3A2, DAG1 and FHIT) that warrant further investigation." (PMID 39897774, 2025). "Three replicated loci were previously reported (ITIH3, FHIT, BAG5), but the other seven (ZNF804A, MIR3143, PSORS1C2, STK19, SPATA31D1, RTN1, TCF4) were novel for depression." (PMID 30626913, 2020). "Other potential candidate genes whose function might provide new insights in the pathophysiological process of depression include LTBP3, BTN3A2, DAG1 and FHIT." (PMID 39897774, 2025).
ovarian carcinoma (5 papers, 1998 to 2017). A malignant neoplasm originating from the surface ovarian epithelium. "The present data suggest that inactivation of the FHIT gene by loss of expression is one of the important molecular events associated with the genesis of ovarian carcinoma, especially of high-grade serous carcinoma." (PMID 11461085, 2001). "Allelic losses at D3S1300 and D3S4103, both located within intron 5 of FHIT were detected in 5/24 (21%) and 5/25 (20%) informative ovarian carcinomas, respectively." (PMID 11461085, 2001). "Fifty-four primary ovarian carcinomas were studied by reverse transcription of FHIT mRNA followed by polymerase chain reaction (PCR) amplification and sequencing of products." (PMID 9569038, 1998). "As alterations of chromosome 3p are common events in ovarian cancers with breakpoint sites at 3p14.2, we decided to investigate the role of FHIT in human ovarian tumorigenesis." (PMID 9569038, 1998). "Since it is not known which of these two pathways is active in ovarian cancer, we investigated both and found FHIT gene expressed in all tumors." (PMID 28423547, 2017).
invasive carcinoma (4 papers, 1999 to 2017). A carcinoma that is not confined to the epithelium, and has spread to the surrounding stroma. "In contrast, underexpression of FHIT was associated with lesions with increasing severity (χ2trend=114.31), including four out of 12 DCIS and 14 out of 34 invasive carcinomas." (PMID 17164758, 2007). "Three DCIS and seven invasive carcinomas with normal EGFR expression underexpressed FHIT, whereas two DCIS and 11 invasive carcinomas with normal FHIT expression overexpressed EGFR." (PMID 17164758, 2007). "FHIT underexpression was found in 14 out of 34 (41%) of invasive carcinomas and in four out of 12 (33%) of DCIS." (PMID 17164758, 2007). "Although some studies showed the trends of reduced FHIT expression in microinvasive and invasive carcinoma, and a relationship between FHIT expression and tumor invasion, EMT and metastasis, our study revealed an unrecognized role for FHIT in modulation of expression of miRNA genes." (PMID 25340791, 2014). "Three DCIS and seven invasive carcinomas with normal EGFR expression underexpressed FHIT, which suggest that detection of FHIT expression could be of use either alone or with other markers such as EGFR, in identifying a subset of proliferative breast lesions with malignant potential." (PMID 17164758, 2007). "However, the incidence of FHIT expression in BBD lesions in the absence of invasive carcinoma was unclear." (PMID 17164758, 2007). "Although FHIT underexpression and EGFR overexpression followed a overall similar distribution in proliferative BBD lesions and in invasive carcinomas, they were not always concordant in individual cases." (PMID 17164758, 2007).
lymph node metastasis (4 papers, 2004 to 2022). "Expression levels of FHIT are reduced in colorectal adenocarcinoma, suggesting an association with copy number deletion, where lower FHIT protein levels are seen with Dukes’ stages C and D and lymph node metastasis." (PMID 35565354, 2022). "In agreement with previous studies, allelic deletion of the FHIT locus did not correlate with sex, age, staging, lymph node metastasis and survival." (PMID 15150628, 2004). "However, FHIT LOH was not correlated overall with a variety of clinical parameters including sex, smoking status, staging, lymph node metastasis and survival." (PMID 15150628, 2004).
lymphoma (4 papers, 2021 to 2025). A malignant (clonal) proliferation of B- lymphocytes or T- lymphocytes which involves the lymph nodes, bone marrow and/or extranodal sites. "Gene expression studies showed that the fragile histidine triad (FHIT) gene had reduced expression in canine lymphoma cell lines." (PMID 41012800, 2025). "Among patients with ATL disease acute (74.2%) and chronic (88.6%) ATL patient samples were overwhelmingly represented by FHIT gene methylation, whereas 45 and 20% of smoldering and lymphoma-type ATL patient samples were found to have methylated FHIT." (PMID 34092254, 2021). "Since the percentage of circulating ATL cells is very low in the lymphoma type (less than 5%), these results strongly suggest that non-infected PBMC from lymphoma-type ATL carry a methylated FHIT gene." (PMID 34092254, 2021).
acute myeloid leukemia (3 papers, 2021 to 2025). Acute myeloid leukemia (AML) is a group of neoplasms arising from precursor cells committed to the myeloid cell-line differentiation. "In hematological malignancies, FHIT methylation has been seen in some cases of myelodysplastic syndrome (MDS), acute myeloid leukemia (AML), and acute lymphoblastic leukemia (ALL), and chronic myelogenous leukemia (CML)." (PMID 34092254, 2021).
cholangiocarcinoma (3 papers, 2014 to 2019). A carcinoma that arises from the intrahepatic biliary tree (intrahepatic cholangiocarcinoma) or from the junction, or adjacent to the junction, of the right and left hepatic ducts (hilar cholangiocarcinoma). "Adjacent to this was another CN loss on 3p containing the tumour suppressor FHIT, which has been observed in 60–70% of cholangiocarcinoma patients." (PMID 31795195, 2019). "Our previous studies showed that the loss of FHIT protein may play an important role in the carcinogenesis and prognosis of cholangiocarcinoma." (PMID 24757411, 2014). "The transcription deletion of FHIT was detectable in intrahepatic cholangiocellular carcinomas induced by N-nitrosobis (2-oxopropyl) amine in female Syrian golden hamsters." (PMID 29296239, 2017). "We investigate the potential pathway in which FHIT regulates cells proliferation and apoptosis in cholangiocarcinoma." (PMID 24757411, 2014). "Data revealed that the overexpression of FHIT andthe addition of LY294002 could suppress cholangiocarcinoma cell growth and induce apoptosis in QBC939 cells." (PMID 24757411, 2014). "The aim of this study is to investigate whether FHIT plays an important role in the development and prognosis of cholangiocarcinoma through the inactivation of the PI3K-Ak signaling pathway." (PMID 24757411, 2014). "In conclusion, the PI3K-Akt pathway may play an important role in FHIT-induced proliferation and apoptosis in cholangiocarcinoma cells." (PMID 24757411, 2014). "To determine whether FHIT can regulate this pathway in cholangiocarcinoma QBC939 cells, we constructed an FHIT expression plasmid and used it to transfect QBC939 cells." (PMID 24757411, 2014). "All of these results indicated that blocking up PI3K/Akt pathway, as the effect of FHIT, could suppress cholangiocarcinoma cell growth and apoptosis." (PMID 24757411, 2014). "Our previous study showed that FHIT could suppress cholangiocarcinoma cells growth and promote apoptosis." (PMID 24757411, 2014). "Therefore, we speculated that FHIT-induced apoptosis occurs via the inactivation of the PI3K-Akt signaling pathway in cholangiocarcinoma." (PMID 24757411, 2014). "Our study found the expression of survivin in cholangiocarcinoma was higher than normal tissue adjacent to carcinoma and had negative correlation with the expression of FHIT protein by immunohistochemistry (data not shown)." (PMID 24757411, 2014). "Understanding the relationship between FHIT and PI3K-Akt pathway could provide useful information not only for the early detection of cholangiocarcinoma, but also for the development of novel therapeutic strategies." (PMID 24757411, 2014).
colorectal adenocarcinoma (3 papers, 1999 to 2022). The most common type of colorectal carcinoma. "In a study involving 100 colorectal adenocarcinomas, Mady and Melhem (2002) found that overexpression of FHIT is directly proportional to the rate of apoptosis." (PMID 17164758, 2007). "Forty-five colorectal adenocarcinomas were examined for alterations in the HIT family genes FHIT and PKCI-1/HINT by a combination of reverse transcriptase polymerase chain reaction and DNA sequencing." (PMID 10555761, 1999).
glioma (3 papers, 2015 to 2024). A benign or malignant brain and spinal cord tumor that arises from glial cells (astrocytes, oligodendrocytes, ependymal cells). "Expression of APOBEC3B was significantly negatively correlated with FHIT expression in glioma cell lines (ρ = − 0.407, padj = 0.0022, n = 79, Ntests = 230)." (PMID 29642934, 2018). "Moreover, WWOX overexpression was shown to promote the immune response in a glioma model while FHIT positively regulates expression of MHC class I molecules on cancer cells." (PMID 26375816, 2015). "However, this did not appear to be the case because in our analysis of glioma cell lines, which included astrocytoma, lower-grade glioma, and glioblastoma multiforme cell lines, mean APOBEC3B and FHIT expression levels were comparable to those in the pan-cancer dataset." (PMID 29642934, 2018).
invasive breast carcinoma (3 papers, 2007 to 2023). A carcinoma that infiltrates the breast parenchyma. "Two of three lesions with FHIT underexpression and five of five lesions with normal FHIT expression progressed subsequently to invasive breast cancer, but the difference was not significant (P=0.375)." (PMID 17164758, 2007).